SLC30A8 (solute carrier family 30 member 8)
Diseases named in the same sentence as SLC30A8 in open-access papers (continued):
Sharing a sentence is not in itself a finding about the gene and the disease.
type 1 diabetes (18 papers, 2009 to 2025). "In the future, the influence of variants in SLC30A8 on the rate of progression to clinical type 1 diabetes should be clarified, especially in those with age of onset above 15 years." (PMID 31444530, 2019). "It was found that SLC30A8 gene encoded Zn transporter 8 is linked with the occurrence of type 1 diabetes." (PMID 27071614, 2016). "ZnT8/SLC30A8 is described as a type 1 diabetes susceptibility gene." (PMID 29055035, 2017). "Therefore, we evaluated the relevance of ZnT8A for type 1 diabetes (T1D) diagnosis and the role of ZnT8 coding gene (SLC30A8) in T1D predisposition." (PMID 28303020, 2017). "Finally, we re-examined the association of rs13266634 in SLC30A8 with ZnT8A and type 1 diabetes." (PMID 22526605, 2012). "The gene SLC30A8, which confers certain disposition to non-insulin-dependent diabetes, found only in the Guanajuato population." (PMID 40997121, 2025). "A member of this family, ZnT8 (SLC30A8)—and in particular, the C-terminal domain of the transporter (amino acids 268–369)—was identified as a target of autoantibodies in type-I Diabetes Mellitus (DM)." (PMID 35409183, 2022). "Newly diagnosed type 1 diabetes patients with the CC (ZnT8R/R) and CT (ZnT8R/W) genotypes of the rs13266634 SNP of the SLC30A8 gene had higher stimulated C-peptide levels the first year after onset compared with TT (ZnT8W/W) subjects." (PMID 34983671, 2022). "The most important beta cell autoantigens in type 1 diabetes (Ins1/2, Slc30a8, Ica1, Gad1, Ptprn2) were expressed at higher levels in Zbed6-KO islets." (PMID 34296320, 2021). "No genetic association between SLC30A8 and type 1 diabetes has been found." (PMID 19243577, 2009). "Also, NKX6.3, DLL4, SLC30A8, and STX1A, which play key roles in insulin synthesis and release, are predicted to be targeted by miR-214-5p, which was significantly upregulated in FOXA2-deficient islets, and has been previously reported to be associated with type 1 diabetes (T1D)." (PMID 38916841, 2024). "The chronic autoimmune reaction in type 1 diabetes is directed towards specific beta cell antigens, which include the beta cell surface proteins insulin, PTPRN (which is also known as insulinoma antigen 2 or IA-2) and zinc transporter 8 (also referred to as ZNT8 or SLC30A8)." (PMID 22460761, 2012).
Obesity (13 papers, 2008 to 2025). Accumulation of substantial excess body fat. "The researchers concluded that zinc supplementation and a high zinc/iron intake ratio may lower the risk of T2DM, but these relations could be modified by obesity and the SLC30A8 genotype." (PMID 30091069, 2019). "It is impossible to deduce from this observational setting whether obesity per se influences the function of the SLC30A8 gene variant." (PMID 29093761, 2017). "Variants in the SLC30A8 gene can impair insulin secretion and action, key features in T2DM and insulin resistance, which are precursors to obesity." (PMID 41009965, 2025). "We genotyped nine SNPs reported in GWAS of obesity and/or T2D, including SNPs in HHEX, KCNJ11, SLC30A8, FTO, CDKN2, CDKAL1, TCF2, and the rs9300039 SNP in an intergenic region, in 561 colon cancer cases and 721 population controls." (PMID 27990199, 2009). "Notably, we made the novel finding that T2D risk, as conferred by HNF1A, GCK, and SLC30A8 genetic variants, may also be modified in the presence/absence of obesity." (PMID 18498634, 2008).
Insulin resistance (5 papers, 2007 to 2025). Increased resistance towards insulin, that is, diminished effectiveness of insulin in reducing blood glucose levels. "The only other study in Mexican Americans from the Arizona Insulin Resistance Registry also could not find significant association between SLC30A8 SNPs and T2D." (PMID 27896278, 2016). "The genetic variants related to T2DM in Caucasians are mainly related to insulin resistance, but those in Asians, including Chinese, Japanese, and Koreans, are involved in insulin secretion (GLP1R, PAX4, HNF4A, SLC30A8, HHEX, CDKAL1, CDKN2A/B, and GCKR)." (PMID 35956399, 2022).
asthma (4 papers, 2013 to 2022). "A GWAS including Japanese and Korean pediatric asthma patients and controls, identified SLC30A8 (Solute Carrier Family 30 member 8) SNP (rs3019885—> T/G) to associate strongly with pediatric asthma." (PMID 33133517, 2020). "Two large-scale GWAS for asthma found that SLC22A5 and SLC30A8 were significantly associated with asthma." (PMID 30239845, 2019). "Genome-wide association (GWA) studies on asthma have suggested that several polymorphisms in several genes, including ORMDL3-GSDMB, DENND1B, HLA-DP, SLC30A8, IL1RL1-IL18R1, IL33, SMAD3, TSLP, and NOTCH4 are associated with asthma." (PMID 23861779, 2013). "SLC30A8 has been implied in blood sugar levels and TMEM232 in allergic rhinitis and asthma." (PMID 34775485, 2022).
breast carcinoma (3 papers, 2019 to 2023). "SLC30A8 is aberrantly expressed in breast cancer and glioblastoma tumors, and decreased expression of SLC30A8 could contribute to the uncontrolled growth, proliferation, and tumor maintenance of glioblastoma multiforme cells." (PMID 33110097, 2020).
Gestational Diabetes Mellitus (3 papers, 2023 to 2026). "SLC30A8, also known as zinc transporter 8 (ZnT8), is a pivotal gene implicated in the pathogenesis of Gestational Diabetes Mellitus (GDM)." (PMID 38694942, 2024). "The SLC30A8 gene, encoding a crucial zinc transporter, may be affected by mutations that affect pancreatic beta cell function, potentially increasing gestational diabetes mellitus susceptibility." (PMID 38694942, 2024). "This study aimed to investigate the impact of SLC30A8 gene polymorphisms on gestational diabetes mellitus (GDM)." (PMID 37324267, 2023).
Glucose intolerance (2 papers, 2011 to 2013). Glucose intolerance (GI) can be defined as dysglycemia that comprises both prediabetes and diabetes. "Specific β-cell inactivation of SLC30A8 in mouse results in glucose intolerance and recently published meta-analysis results revealed a significant association between the rs13266634 C/T polymorphism of SLC30A8 and T2DM and IGT." (PMID 22208362, 2011). "Several reports have found diet-dependent glucose intolerance and insulin secretion abnormalities in SLC30A8 knockout mice." (PMID 23334806, 2013).
Impaired glucose tolerance (2 papers, 2012 to 2015). An abnormal resistance to glucose, i.e., a reduction in the ability to maintain glucose levels in the blood stream within normal limits following oral or intravenous administration of glucose. "Surprisingly, however, this same study demonstrated a reduction in insulin secretion in Slc30a8 KO mice during an intraperitoneal glucose tolerance test (IPGTT) as well as impaired glucose tolerance." (PMID 22829903, 2012).
insulinoma (2 papers, 2014 to 2015). "SLC30A8 encodes a zinc transporter which is expressed solely in secretory vesicles of β-cells and the overexpression of SLC30A8 in insulinoma cells increases glucose-simulated insulin secretion." (PMID 25927708, 2015).
atherosclerosis (1 paper, 2013). A disease characterized by the build-up of fatty material and calcium deposition in the arterial wall resulting in partial or complete occlusion of the arterial lumen. "The Howard University Family Study found nominal significance (p<0.05) at the SLC30A8 locus, the Multi-Ethnic Study of Atherosclerosis at MTNR1B, and the Candidate Gene Association Resource at G6PC2, GCK, and MTNR1B." (PMID 24063630, 2013).
central obesity (1 paper, 2025). "PSRC1 rs599839 in a dominant model (AA + GA vs. GG) with OR = 3.18 (p = 0.041), SLC30A8 rs1326634 in a recessive model (CC vs. TC + TT) (OR = 2.38; p = 0.004), both showing increased susceptibility to central obesity." (PMID 41009965, 2025). "In terms of strengths, the present work showed that a simple genetic analysis (SLC30A8 rs1326634) may serve as a genetic tool for identifying a higher propensity for central obesity in women." (PMID 41009965, 2025).
cervical cancer (1 paper, 2022). A primary or metastatic malignant neoplasm involving the cervix. "And a high expression of SLC30A1, SLC30A6, SLC30A8 and SLC30A10 was associated with worse overall survival in cervical carcinoma patients." (PMID 35154468, 2022). "Data in the UALCAN tool revealed that mRNA expressions of SLC30A1, SLC30A7 and SLC30A10 were significantly higher in cervical cancer tissues, while SLC30A2 and SLC30A8 mRNA levels were decreased compared to normal tissues." (PMID 35154468, 2022). "For tumor stages, SLC30A1, SLC30A7 and SLC30A10 groups significantly varied, whereas SLC30A2, SLC30A3, SLC30A4, SLC30A5, SLC30A6, SLC30A8 and SLC30A9 did not significantly differ in cervical carcinoma." (PMID 35154468, 2022).
diabetic nephropathy (1 paper, 2020). "The genetic association between the SLC30A8 gene and the increased risk of T2DM and diabetic nephropathy (DN) was investigated, by examining the DNA methylation status of six CpG sites in the SLC30A8 promoter using blood samples." (PMID 32653024, 2020).
diabetic retinopathy (1 paper, 2013). "Our study showed nominal associations between variants at the SLC30A8 and MTNR1B loci with any diabetic retinopathy." (PMID 24244560, 2013).
Hyperglycemia (1 paper, 2019). An increased concentration of glucose in the blood. "Because of its known function, the initial hypothesis was that reduced ZnT8 activity would increase risk of T2D; however, when numerous Slc30a8 knockout mice were subsequently created and tested for a variety of glycemic phenotypes, no consistent effects on hyperglycemia emerged." (PMID 30957210, 2019).
ovarian carcinoma (1 paper, 2022). A malignant neoplasm originating from the surface ovarian epithelium. "However, no related researches of SLC30A8 and POLR3H have been studied in ovarian cancer." (PMID 35769811, 2022).
tumor (5 papers, 2016 to 2025). "In addition, regulatory data suggest that the SLC30A8 locus might play a role in survival through the modulation of specific transcription factors implicated in tumour promotion and dissemination." (PMID 27437873, 2016). "The SLC30 family, including SLC30A8 (ZnT8) in HCC, regulates zinc homeostasis, which affects insulin secretion and indirectly influences the tumor microenvironment through genetic variants linked to T2DM risk." (PMID 41425581, 2025). "Western blot analysis of protein extracted from mouse tumor samples showed increased SLC30A8 protein levels in three out of the four miR-143-inh samples (miR-143-inh-1, 3, 4) compared to the NC-inh group." (PMID 30322013, 2018). "The decreased expression of all these genes (including SLC30A8), as a result of the aberrant overexpression of miR-143, could contribute to the uncontrolled growth, proliferation, and tumor maintenance of GBM cells." (PMID 30322013, 2018). "As metabolic rewiring has been recently coined as a hallmark of cancer, further studies should be performed to uncover the role of miR-143 and its target gene SLC30A8, in metabolism pathways contributing to GBM progression and tumor maintenance." (PMID 30322013, 2018).
retinopathy (1 paper, 2013). "Moreover, for any retinopathy, there were several nominally significant associations with SNPs close to the ANK1, SLC30A8, MTNR1B, TMPRSS6 and HK1 loci." (PMID 24244560, 2013).
SLC30A8 also shares sentences with these, for which no sentence is quoted: cancer (3 papers); metabolic syndrome (3); prediabetes (3); Hypertension (2); Zinc deficiency (2); alcohol dependence (1); allergic rhinitis (1); colon cancer (1); colorectal cancer (1); dyslipidaemia (1); esophagal cancer (1); glioblastoma (1); glucose metabolism disorder (1); Hypoglycemia (1); invasive breast carcinoma (1); kidney (1); maturity onset diabetes of the young (1); neurodegenerative disease (1); oesophageal cancer (1); schizophrenia (1); thalassemia (1); vestibular neuritis (1).